EPX (eosinophil peroxidase)
Diseases named in the same sentence as EPX in open-access papers (continued):
Sharing a sentence is not in itself a finding about the gene and the disease.
allergic asthma (6 papers, 2015 to 2024). A asthma with a basis in a pathological type I hypersensitivity reaction. "Our findings indicate that EPX will be a valuable biomarker, especially for translational research examining response to candidate therapeutics in females for allergic asthma." (PMID 35837410, 2022). "At the same time, eosinophil invasion, which is characteristic of allergic asthma, was determined according to eosinophil peroxidase (EPO) activity." (PMID 26132811, 2015). "Upon allergen exposure, they generate ROS and release eosinophil peroxidase, an enzyme that catalyzes the bromination of the amino acid tyrosine, which contribute to vascular dysfunction and may partially explain the attenuated effect of rosuvastatin/Ach in the allergic asthma group." (PMID 39683498, 2024). "Of note, multiple DMRs (EPX, ACOT7 and SORCS2 genes) were overlapping across phenotypes like FeNO, allergic asthma, environmental IgE sensitization, and total IgE." (PMID 35344303, 2022). "The replication external cohort for allergic asthma confirmed 61% differentially methylated CpGs (58 CpGs), including several sites annotated to the ACOT7, ZFPM1, PRG2, EPX and EVL genes." (PMID 35344303, 2022). "In addition, multiple DMRs with five or more CpGs (EPX (eosinophil peroxidase), ACOT7, SORCS2 genes) were overlapping across phenotypes like FeNO, allergic asthma, environmental IgE sensitization, and total IgE." (PMID 31300640, 2019).
airway allergy (4 papers, 2022 to 2026). "The immunomodulatory effects of RosA on respiratory allergies induced by the Blomia tropicalis (Bt) mite in A/J mice showed remarkable reductions in total inflammatory cells and eosinophils, as well as decreased eosinophil peroxidase activity and IL‐4 levels in BALF." (PMID 41523289, 2026).
allergic disease (4 papers, 2019 to 2025). An immune response that occurs following re-exposure to an innocuous antigen, and that requires the presence of existing antibodies against that antigen. "They release a distinct set of mediators, including eosinophil-derived neurotoxins, major basic proteins, and eosinophil peroxidase, which contribute to tissue remodeling and the chronicity of allergic diseases." (PMID 40258807, 2025). "The AR response include high amounts of specific IgE in the serum, high amounts of allergy relative mediators (eosinophil peroxidase and tryptase), and Th2 cytokines (IL-4, IL-5, IL-13) in nasal secretions, and high total nasal symptom scores (TNSS)." (PMID 38783329, 2024). "Classical eosinophil functions in the context of allergic diseases or host infection with microbial pathogens, including production of lipid mediators and cationic proteins (EPX, MBP and eosinophil cationic protein), may be pro- or antitumorigenic depending on tissue setting." (PMID 38195933, 2024).
parasitic infection (4 papers, 2017 to 2022). "The gene encodes eosinophil peroxidase, an enzyme expressed in eosinophils and released at sites of parasitic infection or allergic stimulation." (PMID 29046734, 2017). "The EPx enzyme is involved in killing parasites and implicates eosinophils in the direct control of parasitic infections." (PMID 35335625, 2022).
airway hyperresponsiveness (3 papers, 2021 to 2025). "Furthermore, eosinophils release cytotoxic granules containing major basic proteins and eosinophil peroxidase, which can cause epithelial damage and contribute to airway hyperresponsiveness and obstruction." (PMID 40244222, 2025). "We analyzed airway hyperresponsiveness (AHR), cytokines in bronchoalveolar lavage fluid (BALF), inflammatory cell counts, and the expression levels of NFκB, Nrf2, EPx, and EDN in the lung tissue, as well as the level of ROS in the lung tissue and BALF." (PMID 34089243, 2021). "All treatment groups were compared to sensitized untreated, or normal mice using histopathologic examination, electron microscopy (EM), airway hyperresponsiveness (AHR) to Methacholine (Mch) challenge, and eosinophil peroxidase activity (EPO) measurements in bronchioalveolar lavage (BAL)." (PMID 34766166, 2021).
atopic dermatitis (3 papers, 2011 to 2022). "Previous studies concerning children with atopic dermatitis and suspected food allergy revealed the usefulness of fecal eosinophil-derived proteins (eosinophil cationic protein [ECP], eosinophil protein-X [EPX]) in diagnostic workup." (PMID 33003355, 2020). "In order to determine if eosinophil localization to nerves in the skin occurs in atopic dermatitis biopsies, we first performed single immunohistochemistry with an antibody to eosinophil peroxidase (EPO), a protein present in eosinophil granules." (PMID 21811556, 2011).
bronchiectasis (3 papers, 2023 to 2025). Segmental, irreversible dilation of the bronchial tree resulting in the accumulation of secretions which leads to obstruction. "In bronchiectasis, increased sputum eosinophils are related to greater bronchodilator reversibility and higher levels of FeNO, IL-13 and an increase in sputum Eosinophil Peroxidase (EPX)." (PMID 41149860, 2025). "Eosinophil-specific inflammatory biomarkers, such as sputum eosinophil peroxidase, which significantly increase in severe bronchiectasis and during exacerbations requiring hospitalization, may better characterize this disease endotype." (PMID 40589741, 2025).
allergic rhinitis (2 papers, 2020 to 2023). Inflammation of the nasal mucous membranes caused by an IgE-mediated response to external allergens. "In conclusion, our study reveals that elevated levels of activated and pathogenic eosinophils are a feature of moderate-severe allergic rhinitis and associated with higher production of ECP, EPX, and IL-4 in the peripheral blood." (PMID 32855977, 2020).
atopic asthma (2 papers, 2016 to 2019). An asthma that is characterized by symptoms that are triggered by an allergic reaction caused by inhaled allergens such as dust mite allergen, pet dander, pollen and mold. "Eosinophils may be another source of IL-17, as suggested by double immunostaining of IL-17 and EPX, and by the significant correlation between IL-17+ cells and eosinophil numbers in atopic asthma patients." (PMID 27552197, 2016).
eosinophilic diseases (2 papers, 2018). "There is an increasing interest in developing novel eosinophil peroxidase (EPO) inhibitors, in order to provide new treatment strategies against chronic inflammatory and neurodegenerative diseases caused by eosinophilic disorder." (PMID 30284485, 2018).
Granuloma (2 papers, 2022 to 2025). A compact, organized collection of mature mononuclear phagocytes, which may be but is not necessarily accompanied by accessory features such as necrosis. "Immunofluorescence staining showed that eosinophils (detected with eosinphil-specific marker, EPX (Eosinophil peroxidase)) predominantly localize around STm containing CD11b+ foci, which are indiciative of granuloma structures." (PMID 39801515, 2025).
melanoma (2 papers, 2022 to 2024). A malignant, usually aggressive tumor composed of atypical, neoplastic melanocytes. "Furthermore, our results reveal the association between elevated AEC, ECP and EPX levels in the peripheral blood and delayed relapse in advanced-stage melanoma patients." (PMID 36428768, 2022). "Since infiltration of Siglec-8, ECP and EPX expressing eosinophils, as well as CD8+ effector T-cells could previously be observed in the tissue samples of melanoma patients, their correlation was further investigated." (PMID 36428768, 2022). "Moreover, eosinophil counts and activity markers such as eosinophil cationic protein (ECP) and eosinophil peroxidase (EPX) were measured in the serum before therapy start and before the 4th infusion of ICI in 45 metastatic unresected melanoma patients." (PMID 36428768, 2022).
metastatic melanoma (2 papers, 2022 to 2024). A melanoma that has spread from its primary site to another anatomic site. "High baseline levels of eosinophil count, serum ECP and EPX were linked to prolonged progression-free survival in metastatic melanoma." (PMID 36428768, 2022). "Furthermore, high baseline eosinophil count, serum ECP, and eosinophil peroxidase levels were associated with prolonged progression-free survival (PFS) in metastatic melanoma under immune checkpoint inhibition." (PMID 38756652, 2024). "In addition, high levels of AEC, ECP and EPX in the blood of metastatic melanoma patients showed prognostic value, suggesting their future potential as serological biomarkers." (PMID 36428768, 2022). "Consequently, in the second part of this study, we analyzed blood samples from metastatic melanoma patients to determine whether eosinophils and their activity markers ECP and EPX could act as prognostic biomarkers." (PMID 36428768, 2022).
Obesity (2 papers, 2024). Accumulation of substantial excess body fat. "EPX has both anti-inflammatory and pro-inflammatory effects and its expression increases in obesity." (PMID 38483771, 2024). "Paralleling AT-EOS content, we found EPX mRNA to be significantly decreased in patients with obesity compared with lean controls (P = 0.003 and P = 0.02, respectively), regardless of the fat depot tested." (PMID 38206766, 2024).
primary biliary cholangitis (2 papers, 2014 to 2023). Primary biliary cholangitis (PBC) is a chronic and slowly progressive cholestatic liver disease of autoimmune etiology characterized by injury of the intrahepatic bile ducts that may eventually lead to liver failure. "Patients with primary biliary cirrhosis (PBC) display decreased levels of antioxidant vitamins (A, C and E), excess HOCl release associated with eosinophil peroxidase, and decreased GST expression." (PMID 24876913, 2014).
Acute Appendicitis (1 paper, 2023). "Eosinophilic cationic protein and eosinophil peroxidase concentrations are elevated in serum and appendicular lavage fluid in patients with acute appendicitis." (PMID 37240441, 2023).
acute respiratory distress syndrome (1 paper, 2024). Progressive and life-threatening pulmonary distress in the absence of an underlying pulmonary condition, usually following major trauma or surgery. "Plasma EPX levels were higher in patients with acute respiratory distress syndrome (ARDS) versus those at risk." (PMID 39255040, 2024).
acute respiratory failure (1 paper, 2024). Life-threatening respiratory failure that develops rapidly. "Next, in a cohort of mechanically ventilated patients with acute respiratory failure at the University of Pittsburgh Medical Center, we measured plasma eosinophil peroxidase (EPX) as a surrogate marker for eosinophil levels." (PMID 39255040, 2024).
ankylosing spondylitis (1 paper, 2023). An autoimmune chronic inflammatory disorder characterized by inflammation in the vertebral joints of the spine and sacroiliac joints. "While anti-EPX is the main antigenic target of AEOSA, anti-ECP seems to be found in rare cases of ulcerative colitis and ankylosing spondylitis." (PMID 37153639, 2023). "All anti-EPX/anti-ECP double-positive AEOSA+/ANCA− sera (6/6) were found in patients with a history of gastrointestinal tract disease and/or autoimmune disease (with 3/3 cases of ankylosing spondylitis)." (PMID 37153639, 2023). "In this regard, the detection of anti-ECP in our cohort may define a more precise patient group as all AEOSA+/ANCA− sera displaying both anti-EPX and anti-ECP reactivity appeared mainly in patients with either gastrointestinal tract inflammation and/or ankylosing spondylitis." (PMID 37153639, 2023).
atherosclerosis (1 paper, 2023). A disease characterized by the build-up of fatty material and calcium deposition in the arterial wall resulting in partial or complete occlusion of the arterial lumen. "It is hypothesized that chemokine expression during atherosclerosis development theoretically led to the accumulation of eosinophils, which contains proteases such as major basic protein (MBP) or eosinophil peroxidase (EPX) that exacerbate local inflammatory responses and tissue damage." (PMID 37163428, 2023).
chronic spontaneous urticaria (1 paper, 2025). "In chronic spontaneous urticaria (CSU), the significance of serum Eosinophil Peroxidase (EPO) and Major Basic Protein (MBP) levels as indicators of disease severity and response to antihistamine treatment is currently inadequately understood." (PMID 41218021, 2025).
esophagitis (1 paper, 2024). An acute or chronic inflammatory disease affecting the esophageal wall. "iNOS and nitrotyrosine are significantly overexpressed in patients with EoE and GERD compared with healthy controls, but only eosinophil peroxidase could differentiate the two types of esophagitis." (PMID 38679488, 2024).
loiasis (1 paper, 2018). Loiasis is a form of filariasis (see this term), caused by the parasitic worm Loa loa, endemic to the forest and savannah regions of Central and Western Africa. "Earlier studies on onchocerciasis, lymphatic filarisis, schistosomiasis, and loiasis showed that ECP and EDN/EPX levels were elevated." (PMID 29479356, 2018). "In our study, we observed that there was a positive correlation between plasma levels of ECP, EPX and MBP, and the AEC, a finding similar to that seen in loiasis." (PMID 29479356, 2018).
pneumonia (1 paper, 2024). An acute, acute and chronic, or chronic inflammation focally or diffusely affecting the lung parenchyma, caused by an infection in one or both of the lungs (by bacteria, viruses, fungi, or mycoplasma.). "Patients with a diagnosis of pneumonia also had higher EPX plasma levels compared with those without pneumonia." (PMID 39255040, 2024).
renal fibrosis (1 paper, 2022). A final common manifestation of a wide variety of chronic kidney diseases characterized by glomerulosclerosis and tubulointerstitial fibrosis. "And in animal models, the loss of eosinophil peroxidase could reduce renal fibrosis." (PMID 35109941, 2022).
vasculitis (1 paper, 2023). "This link was stronger for anti-MPO/anti-EPX double-positive patients as all such patients had a history of thyroid disease or vasculitis." (PMID 37153639, 2023). "All anti-EPX/anti-MPO double-positive AEOSA+/ANCA+ sera (5/5) were found in patients with a history of thyroid disease or vasculitis." (PMID 37153639, 2023). "Despite the presence of autoantibodies against EPX, neither vasculitis nor thyroid disease was reported in the previously studied cohorts." (PMID 37153639, 2023).
tumor (21 papers, 2011 to 2025). "The release of substances such as MBP1—which disrupts the integrity of lipid bilayers of cells—and EPX—which induces oxidative stress—can induce cell death, creating a profound antitumor effect within the tumor microenvironment." (PMID 40678607, 2025). "On one hand, eosinophils directly attack tumor cells via eosinophil peroxidase (EPX) or eosinophil-derived neurotoxin (EDN), or indirectly stimulate macrophages to release TNF-α and H2O2." (PMID 40380196, 2025). "The high variability of eosinophil peroxidase, a granulocyte marker, indicated pronounced differences in the tumor-immune microenvironment in this tumor." (PMID 41418981, 2025). "To query the presence of eosinophils in human PDAC, we stained three tumor microarrays containing surgically resected specimens from independent populations of individuals with PDAC for the eosinophil marker EPX." (PMID 38195933, 2024). "The identified mediators encompass major basic protein (MBP), eosinophil cationic protein (ECP), and eosinophil peroxidase (EPX), all capable of inducing tumor cell lysis in vitro." (PMID 38840908, 2024). "Western blot analysis demonstrated that EPX expression was higher in HCC tissues compared to adjacent non-tumor tissues." (PMID 39308686, 2024). "Eosinophils co-cultured with tumor cells ex vivo produced peroxidase activity and induced tumor cell death, indicating that eosinophils are capable of releasing eosinophil peroxidase (EPX) and killing EO771 tumor cells." (PMID 35756626, 2022). "Eosinophils are activated by IL33, IFN-γ, and IL-5, and activated eosinophils secrete MBP, tumor necrosis factor (TNF)-α, eosinophil peroxidase, and granzyme B, which facilitate the killing of tumor cells." (PMID 35011007, 2021). "In fact, we observed substantial expression of granzyme-B and EPX in tumor-infiltrating EO induced by in vivo exposure to IL-33, at variance with control mice." (PMID 31717819, 2019). "Moreover, eosinophils may polarize tumor-associated macrophages toward an M1 phenotype and mediate direct tumor cell lysis via the release of granule-associated cytotoxic proteins including major basic protein, eosinophil peroxidase, and eosinophil-derived neurotoxin." (PMID 31730503, 2019). "Of note, when eosinophils were co-cultured with tumor cells, a marked polarization of EPX, ECP, and granzyme-B to the immune synapses was observed selectively in IL-33 EO." (PMID 31717819, 2019). "As opposed to controls, tumor tissues from IL-33-treated mice displayed the substantial presence of degranulating tumor-infiltrating eosinophils within tumor necrotic areas, as revealed by co-expression of Siglec-F with EPX and granzyme-B." (PMID 31717819, 2019). "Using our co-culture system, we demonstrated that EPX is released upon co-culture of eosinophils with tumor cells, suggesting that eosinophil degranulation may be a potential mechanism by which eosinophils can kill tumor cells." (PMID 35756626, 2022). "Univariate analysis revealed a higher EPX expression in the cancer areas as compared with normal tissue (p < 0.05) and a correlation of high levels of EPX with higher pathological Tumor Node Metastases (pTNM) stage (p = 0.017) and with lymph node involvement (p = 0.027)." (PMID 35563461, 2022). "Many have theorized eosinophils to have a tumour protective role due to secretion of cytotoxic mediators such as major basic protein, eosinophil cationic protein and eosinophil peroxidase and their ability to increase permeability of tumour killing cytokines into tumour cells." (PMID 25810818, 2015). "Tumor infiltrating immune cells, especially neutrophils and eosinophils, contribute to the generation and maintenance of the tumor inflammatory milieu by producing massively myeloperoxidase (MPO) and eosinophil peroxidase (EPO), respectively." (PMID 32604738, 2020).
tumor (continued). "To validate these findings in intact tumor tissues, we quantified eosinophil abundance by immunohistochemical staining for the eosinophil markers major basic protein (MBP) and eosinophil peroxidase (EPX)." (PMID 38195933, 2024). "While EPX is the only peroxidase present in eosinophil granules, we wanted to confirm that peroxidase activity derived from co-cultures of tumor cells and negatively selected eosinophils was not potentially due to neutrophil-derived myeloperoxidase." (PMID 35756626, 2022). "Previous reports have also demonstrated that eosinophils can directly kill tumor cells via release of cytotoxic granule proteins, such as MBP and EPX; therefore, we evaluated whether eosinophils could kill EO771 tumor cells ex vivo." (PMID 35756626, 2022).